POU2AF3 (POU class 2 homeobox associating factor 3)
Description:
Transcriptional coactivator that specifically associates with POU2F3. This complex drives the development of tuft cells, a rare a rare chemosensory cells that coordinate immune and neural functions within mucosal epithelial tissues.
Synonyms: C11orf93; CASC13; COLCA2; OCA-T2; LOH11CR1G
Tractability: No criterion of Open Targets' tractability assessment is met for any kind of drug.
Gene: Protein-coding gene on chromosome 11 (111,298,546 to 111,308,735, forward strand). Ensembl gene ENSG00000214290.
Subcellular location: Cytoplasm; Nucleus
Subcellular location (Human Protein Atlas): Nucleoplasm; Cytosol
Gene Ontology:
Molecular function: DNA binding; protein binding; transcription coactivator activity; POU domain binding
Biological process: positive regulation of DNA-templated transcription
Cellular component: cytoplasm; cytosol; nucleoplasm; nucleus
Genetic constraint (gnomAD): Loss-of-function variants: 2 observed, 9.01 expected, observed/expected ratio (o/e) 0.22, 90% interval 0.09 to 0.7. That is too few expected variants to judge how well the gene tolerates losing a copy. Missense variants: 229 observed, 247.22 expected, observed/expected ratio (o/e) 0.93, 90% interval 0.83 to 1.03. Synonymous variants: 90 observed, 97.11 expected, observed/expected ratio (o/e) 0.93, 90% interval 0.78 to 1.1.
Homologues: Orthologues: chimpanzee POU2AF3 (98% identical), macaque POU2AF3 (94% identical), pig POU2AF3 (78% identical), dog POU2AF3 (77% identical), rabbit POU2AF3 (75% identical), mouse Pou2af3 (70% identical), guinea pig POU2AF3 (69% identical), rat Pou2af3 (67% identical).
Diseases named in the same sentence as POU2AF3 in open-access papers:
POU2AF3 is named in the same sentence as 16 diseases in open-access papers, as found by Europe PMC text mining. Sharing a sentence is not in itself a finding about the gene and the disease. The quoted sentences say what the papers report.
colorectal cancer (11 papers, 2015 to 2025). A primary or metastatic malignant neoplasm that affects the colon or rectum. "Common genetic variation at 11q23.1 is associated with colorectal cancer (CRC) risk, exerting local expression quantitative trait locus (cis-eQTL) effects on POU2AF2, COLCA1 and POU2AF3 genes." (PMID 39609081, 2025).
sarcoma (3 papers, 2021 to 2025). A usually aggressive malignant neoplasm of the soft tissue or bone. "Recently, it has been proposed that sarcomas harboring a fusion of POU2AF3 with EWSR1 form a novel entity that often originate from the head and neck region, especially from the sinonasal track." (PMID 40134582, 2025). "Further analysis of the MAPK signaling in POU2AF3 fusion sarcomas might also be interesting." (PMID 40134582, 2025). "We established a novel sarcoma cell line, PF1095, with a EWSR1::POU2AF3 fusion." (PMID 40134582, 2025).
infertile (1 paper, 2025). "Pou2af3-/- but not Pou2af2-/- males were also infertile, further decoupling the function of these genes across tissues." (PMID 39609081, 2025).
lung carcinoma (1 paper, 2025). "Our analysis of published ChIPseq data from lung cancer cell lines showed that both POU2AF2 and POU2AF3 are capable of regulating the expression of trans-eQTL targets." (PMID 39609081, 2025).
small cell lung carcinoma (1 paper, 2025). Small cell lung cancer (SCLC) is a highly aggressive malignant neoplasm, accounting for 10-15% of lung cancer cases, characterized byrapid growth, and early metastasis. "POU2AF3 (COLCA2) was described as a coactivator of POU2F3 in the cells and we used a small-cell lung cancer cell line (H526) as a control." (PMID 40134582, 2025).
tumor (8 papers, 2017 to 2025). "To interrogate the tumour suppressive effects of Pou2af2 and Pou2af3 expression independently, we crossed single-knockout colonies onto the multiple intestinal neoplasia, ApcMin/+ model and allowed mice to age until they exhibited a moribund phenotype." (PMID 39609081, 2025). "POU2AF3 expression is reduced in tumour cells which might supress its formation providing protection." (PMID 40506516, 2025). "POU2AF3 is expressed in epithelial, immune and other cells, as well as in tumour cells." (PMID 40506516, 2025).
colonic polyps (1 paper, 2025). "While there was a small increase in size of colonic polyps from ApcMin/+Pou2af3+/- (FDR=0.005), this was not significantly increased in ApcMin/+Pou2af3-/- mice." (PMID 39609081, 2025).
POU2AF3 also shares sentences with these, for which no sentence is quoted: colon cancer (3 papers); B-cell lymphoma (1); breast carcinoma (1); chronic obstructive pulmonary disease (1); colorectal tumor (1); COVID-19 (1); inflammatory bowel disease (1); primary biliary cholangitis (1); viral infection (1).